CHI3L1 (chitinase 3 like 1)
Diseases named in the same sentence as CHI3L1 in open-access papers (continued):
Sharing a sentence is not in itself a finding about the gene and the disease.
Alzheimer disease (83 papers, 2010 to 2026). A progressive, neurodegenerative disease characterized by loss of function and death of nerve cells in several areas of the brain leading to loss of cognitive function such as memory and language. "YKL-40 (CHI3L1) is a glycoprotein secreted by reactive astrocytes and peripheral immune cells, implicated in inflammation and tissue remodeling in Alzheimer’s disease (AD)." (PMID 41425914, 2025). "One of the transcripts significantly changed by CT1812 treatment, CHI3L1, which encodes YKL-40 protein, is expressed in astrocytes and is an interesting biomarker of inflammation in Alzheimer’s disease." (PMID 38319380, 2024). "One of the transcripts significantly changed by CT1812 treatment, CHI3L1, which encodes YKL-40 protein, is expressed in astrocytes and is a biomarker of inflammation in Alzheimer’s disease." (PMID 38319380, 2024). "Some studies have indicated that elevated CSF CHI3L1 are associated with Alzheimer’s disease, multiple sclerosis and Parkinson’s disease." (PMID 36685530, 2022). "More recently, a study in Alzheimer's disease provided even more direct evidence by using human iPSC‐derived neural progenitor cells, demonstrating that CHI3L1 suppresses neuronal differentiation and β‐catenin activity in a CRTH2‐dependent manner." (PMID 41489316, 2026). "Studies measuring glial markers in protein misfolding dementias found significantly elevated CSF CHI3L1 levels in patients with sporadic CJD compared to Alzheimer’s disease, frontotemporal dementia, and healthy controls." (PMID 39827337, 2025). "The two top overlapping DEPs, SMOC1 and CHI3L1, also showed a consistent upregulation in Alzheimer's disease." (PMID 40491829, 2025). "This evidence underscores CHI3L1’s potential as both a biomarker and a therapeutic target in Alzheimer’s disease." (PMID 39827337, 2025). "In this study, we investigated peripheral CHI3L1 expression across the Alzheimer’s disease (AD) spectrum, stratified by APOE genotype, age at onset (AAO), and sex." (PMID 41425914, 2025). "In the present study, we demonstrate that targeting CHI3L1 with the monoclonal antibody (H1) alleviates key pathological features of Alzheimer’s disease, including neuroinflammation, amyloid accumulation, and cognitive impairment, in the Tg2576 mouse model." (PMID 41573517, 2025). "Reportedly, Chi3l1 is significantly increased and a promising biomarker for multiple neurodegenerative diseases, including Alzheimer’s disease (AD), Parkinson’s disease (PD), Huntington’s disease (HD), dementia, and amyotrophic lateral sclerosis (ALS)." (PMID 39769202, 2024). "Increased levels of Chi3l1 in the cerebrospinal fluid (CSF) have been observed in Alzheimer’s disease (AD) and multiple sclerosis (MS)." (PMID 39437409, 2024). "Elevated levels of CHI3L1(YKL40) have been observed in the cerebrospinal fluid (CSF) and brain tissue of individuals with Alzheimer’s disease." (PMID 38543093, 2024). "Research on targeting CHI3L1(YKL40) or inhibiting its activity as a therapy against Alzheimer’s disease is still ongoing." (PMID 38543093, 2024). "The expression of CHI3L1 is strongly upregulated by various inflammatory and immunological diseases, including several cancers, Alzheimer’s disease, and atherosclerosis." (PMID 38177294, 2024). "Previous investigations have demonstrated that CHI3L1(YKL40) is involved in inflammatory processes and neurodegenerative disorders, such as Alzheimer’s disease." (PMID 38543093, 2024). "In Alzheimer disease CSF CHI3L1 levels are elevated prior to development of cognitive symptoms and are predictive of clinical severity." (PMID 36721240, 2023). "Another study by Burman and colleagues in 2018 compared the performance of ELISA, SIMOA, and Luminex xMAP for measuring CSF CHI3L1 levels in patients with Alzheimer’s disease." (PMID 36988727, 2023). "Another study also found sex-, age- and Alzheimer’s disease-related differences in CHI3L1 expression in the brain." (PMID 37221602, 2023).
Alzheimer disease (continued). "In our previous studies, we found that CHI3L1 deficiency attenuates inflammation-induced liver injury, and that administration of an inhibitor of CHI3L1 restores memory by alleviating neuroinflammation in an Alzheimer’s disease mouse model." (PMID 35345530, 2022). "It is also reported that CHI3L1 is up-regulated in patients with chronic neurological disease such as Alzheimer’s disease, bipolar disorder, and schizophrenia." (PMID 35345530, 2022). "Chitinase 3-like-1 (CHI3L1), also known as YKL-40, has been extensively studied as a cerebrospinal fluid biomarker for diseases such as Alzheimer’s disease and dementia." (PMID 35237278, 2022). "Chitinase 3-like 1, also known as YKL-40, is a microglial and/or astrocytic marker believed to reflect the neuroinflammatory process of Alzheimer’s disease." (PMID 34943935, 2021). "YKL-40 is a pro-inflammatory glycoprotein regulated by CHI3L1 in obese populations and is extensively reported to contribute to the progression of Alzheimer’s disease given its contribution to psychiatric diseases." (PMID 29258237, 2017). "Brain tissue homogenate studies have found increased CHI3L1 mRNA in schizophrenia, autism and Alzheimer's disease." (PMID 20540736, 2010). "In addition, increased expression of CHI3L1 in both healthy women and in brain regions affected by late-onset Alzheimer’s disease indicates a possible explanation for the higher prevalence of AD in women than in men80–83." (PMID 38177294, 2024). "It has been suggested that CHI3L1(YKL40) may contribute to the neuroinflammatory response and the formation of amyloid-beta plaques, which are a hallmark of Alzheimer’s disease." (PMID 38543093, 2024). "For example, inhibition of CHI3L1 with the compound K284-6111 prevented amyloid beta-induced neuroinflammation and impairment of recognition memory via inhibition of the NF-κB pathway in an Alzheimer’s disease mouse model." (PMID 34359293, 2021). "Some studies have shown that elevated CHI3L1 in cerebrospinal fluid may predict Alzheimer’s disease and that CHI3L1 is also an inflammatory biomarker for multiple sclerosis." (PMID 33192455, 2020). "Elevated CHI3L1 levels have been reported in various neuroinflammatory and neurodegenerative disorders, including multiple sclerosis, neuromyelitis optica, Alzheimer's disease, and Parkinson's disease, where it is closely associated with glial activation and tissue remodeling." (PMID 41489316, 2026). "Moreover, a deeper investigation into CHI3L1’s role in PD may help distinguish it from other neurodegenerative diseases, such as Alzheimer’s disease, by shedding light on the distinct molecular mechanisms at play in each condition." (PMID 39827337, 2025). "Chi3l1 is significantly correlated with AD core biomarkers such as tau protein and amyloid beta (Aβ), whereas core biomarkers of neurodegeneration, such as tau protein, can accurately distinguish different neurodegenerative diseases, such as Alzheimer’s disease dementia and frontotemporal dementia." (PMID 39769202, 2024). "Elevated levels of PDCD5, ENO1, CHI3L1, PP3R1 and SCRN1 have been observed in CSF from individuals with Alzheimer disease." (PMID 36721240, 2023). "Chitinase 3-like 1 (CHI3L1), chitinase 3-like 2 (CHI3L2), and neuronal pentraxin II (NPTX2) are inflammatory biomarkers of Alzheimer’s disease (AD)." (PMID 32066474, 2020). "In Alzheimer's disease, CD68 (p = 0.026), CD64 (p = 0.002), CHI3L1 (p = 0.016), IL4R (p = 0.005) and CCR2 (p = 0.010) were increased independently of systemic infection." (PMID 30193587, 2018). "Due to the inability to obtain reliable human neural stem cell lines, we were unable to perform in vitro neurogenesis assays to determine whether CHI3L1 directly suppresses neuronal differentiation, as reported in MS, NMOSD, and Alzheimer's disease models." (PMID 41489316, 2026).
Alzheimer disease (continued). "Two DEPs, ‘SPARC-related modular calcium-binding protein 1’ (SMOC1) and ‘chitinase-3 like-protein-1’ (CHI3L1, also known as YKL-40), both well-established markers of Alzheimer's disease, were found across 14 studies constituting the highest overlap among all studies." (PMID 40491829, 2025). "YKL40 is a robust CSF biomarker in other neuroinflammatory diseases, such as Creutzfeld-Jakob and Alzheimer’s disease, and the mouse homolog of human YKL40, CHI3L1, was elevated in brains of LD and APBD models and expression was normalized in rescued LD (DKO) mice." (PMID 39806098, 2025). "The established Alzheimer's disease associated proteins SMOC1 and CHI3L1, as well as other remaining top DEPs were not part of a functionally annotated cluster." (PMID 40491829, 2025). "In our study, the CHI3L1 level was higher in ED patients than in non-ED patients; however, CHI3L1 was unrelated to ED after adjusting for risk factors, which may be due to different pathological and physiological processes of delirium, Alzheimer’s disease, and multiple sclerosis." (PMID 33192455, 2020). "In this regard, Sanfilippo and colleagues in 2017 confirmed that CHI3L1 is produced from activation of microglia and astrocytes during the progression of neurodegeneration in cortex and in the spinal cord of neurodegenerative diseases like MS, ALS, and Alzheimer’s disease." (PMID 36988727, 2023).
dementia (71 papers, 2011 to 2026). Loss of intellectual abilities interfering with an individual's social and occupational functions. "Elevated levels of CHI3L1 have been associated with disease progression and tissue damage in multiple sclerosis, neuromyelitis optica, and HIV-associated dementia, making it a key player in these pathologies." (PMID 39827337, 2025). "It has been also reported that higher CHI3L1 levels mainly reflect a response to both total tau and phosphorylated tau levels in the pre-dementia AD group." (PMID 37047273, 2023). "Previous studies have also demonstrated that higher CSF CHI3L1 levels in individuals with mild AD-type dementia, compared to healthy controls, suggesting that CHI3L1 has potential to discriminate AD from other forms of dementia and be a predictor of disease progression." (PMID 39827337, 2025). "Heterogeneity in the magnitude of the protein-dementia associations was observed among APOEε4 carriers for one NCR1 (one of the top four candidate proteins), GDF15, CHI3L1, and TFF3, each of which showed significant associations with VaD and comparatively weaker associations with AD dementia." (PMID 39482741, 2024). "CHI3L1 concentrations result as consistently high in the dementia phase of AD." (PMID 37047273, 2023). "Reactive astrocyte CHI3L1 levels are consistently elevated in the dementia phase of AD." (PMID 37047273, 2023). "Notably, CHI3L1 levels in CSF showed a stronger correlation in Aβ-positive patients, and higher CSF CHI3L1 levels were reported to be associated with an increased risk of developing AD dementia in individuals without dementia." (PMID 41573517, 2025). "Inflammatory markers such as tumor necrosis factor (TNF), interleukin-6 (IL-6), chitinase-3-like protein 1 (CHI3L1 or YKL-40), and acute phase C reactive protein (CRP) were found to have effects on the brains or peripheral regions of dementia patients." (PMID 37873875, 2023). "Neurogranin (NRG), TAR DNA-binding protein 43 (TDP43), chitinase 3-like 1 (YKL40, cartilage glycoprotein-39), and kallikrein 6 (KLK6) are often found in classical AD and other dementias." (PMID 34944606, 2021). "The study suggested that the markers YKL-40 (CHI3L1), a glycoprotein derived from astrocytes, and GFAP (a marker related to astrogliosis) detected in plasma, could serve as effective indicators, particularly in pre-dementia patients." (PMID 38920976, 2024).
liver fibrosis (69 papers, 2010 to 2025). "CHI3L1 has emerged as a promising alternative biomarker for diagnosing, detecting the progression, and assessing the treatment response of liver fibrosis caused by hepatitis." (PMID 40821115, 2025). "In hepatocellular carcinoma (HCC), CHI3L1 is highly expressed in underlying liver pathologies, such as chronic hepatitis and liver fibrosis." (PMID 40643503, 2025). "We aimed to explore the diagnostic value of CHI3L1 for liver fibrosis in AILDs and to compare its application differences between AILDs and chronic hepatitis B (CHB) patients." (PMID 40352927, 2025). "When diagnosing significant liver fibrosis, the diagnostic efficacy of serum CHI3L1 is superior to that of other non-invasive diagnostic methods, including APRI, FIB-4, GPR, AAR, NLP, and PLR." (PMID 40352927, 2025). "CHI3L1 has been reported as a diagnostic marker for hepatic fibrosis induced by HCV infection in kidney transplant patients, but it is inferior to another non-invasive biomarker, HA." (PMID 40821115, 2025). "CHI3L1, as a potential biomarker for the diagnosis of liver fibrosis, is implicated in the pathogenesis of hepatic fibrosis." (PMID 40352927, 2025). "In contrast, the evaluation of CHI3L1 in ALD as well as AIH-associated hepatic fibrosis has been reported less frequently, underscoring the need for further exploration of the important role of CHI3L1 in their progression and diagnosis." (PMID 38962736, 2024). "Overall, CHI3L1 is important for the diagnosis of advanced NAFLD-associated hepatic fibrosis and increased CHI3L1 expression directly correlates with hepatic fibrosis progression." (PMID 38962736, 2024). "In patients with CHB and an ALT less than twice the ULN, serum CHI3L1 levels are independently associated with advanced liver fibrosis and serve as a potential biomarker for liver fibrosis." (PMID 38962736, 2024). "Most patients with HBeAg-negative chronic hepatitis B have an elevated risk of cirrhosis and liver cancer, and serum Chi3l1 can act as a diagnostic marker and risk factor for liver fibrosis in these patients." (PMID 39769202, 2024). "Serum CHI3L1 is an important diagnostic indicator for CHB liver fibrosis and is important in guiding antiviral therapy." (PMID 38962736, 2024). "Many studies have verified that Chi3l1 can be used to diagnose and evaluate digestive gland-associated inflammatory diseases such as liver injury, liver fibrosis, cholecystitis, and pancreatitis." (PMID 39769202, 2024). "Because of its value as a diagnostic biomarker for liver fibrosis, elucidation of the biological functions of CHI3L1 and potential mechanistic contribution to the development and progression of NASH-related inflammation and fibrosis are warranted." (PMID 37166517, 2023). "High-quality studies with larger sample sizes are required on the diagnostic value of CHI3L1 in liver fibrosis, with multiregional cooperation." (PMID 35360517, 2022). "An article published in 2018 reported a meta-analytic study of the diagnostic value of YKL-40 (CHI3L1) for liver fibrosis, with the same objective as the present study." (PMID 35360517, 2022). "Many studies have been exploring the diagnostic value of serum CHI3L1 for liver fibrosis, but we noticed that the diagnostic value of CHI3L1 is controversial." (PMID 35360517, 2022). "In this meta-analysis, we addressed the diagnostic value of serum CHI3L1 as a promising and strong noninvasive marker of predicting hepatic fibrosis." (PMID 35360517, 2022). "A prior meta-analysis that included nine articles published before 2018 evaluated the diagnostic value of serum YKL-40 (CHI3L1) for liver fibrosis stage." (PMID 35360517, 2022). "In this study, we performed an updated and more comprehensive meta-analysis to get a better view of the diagnostic value of CHI3L1 in liver fibrosis." (PMID 35360517, 2022).
liver fibrosis (continued). "Despite these limitations, our study provides evidence on the particular advantages of serum CHI3L1 over other indicators, and the association between serum CHI3L1 and liver fibrosis diagnosis was a worthy topic for meta-analysis." (PMID 35360517, 2022). "This meta-analysis was carried out to assess the diagnostic performance of serum CHI3L1 for the estimation of liver fibrosis." (PMID 35360517, 2022). "Numerous studies show that CHI3L1 upregulates in liver fibrosis caused by virus infection, alcohol, or the accumulation of liver lipid." (PMID 32929074, 2020). "Previous studies have shown that chitinase 3-like protein 1 (CHI3L1) was a marker for staging of liver fibrosis caused by HCV." (PMID 33082884, 2020). "In the present study, we purposed to determine serum chitinase 3‐like 1 (CHI3L1) expression characteristics in chronic liver diseases monoinfected with hepatitis B virus and analyze its diagnostic value in liver fibrosis." (PMID 31916309, 2020). "The up-regulation of CHI3L1 has been previously linked with fibrosis in other diseases, most notably idiopathic pulmonary fibrosis and liver fibrosis." (PMID 29554127, 2018). "In particular, chitinase 3-like 1 protein, a marker of inflammation that has been linked to schistosome-related hepatic fibrosis, was found to be highest in the older people harbouring infection." (PMID 25101623, 2014). "Furthermore, we observed a positive correlation between serum CHI3L1 levels and the degree of liver stiffness, suggesting a potential association between serum CHI3L1 and liver fibrosis in AILDs patients." (PMID 40352927, 2025). "Therefore, future research should conduct multic - enter prospective studies to further expand the sample size, verify the diagnostic efficacy of CHI3L1 in AILDs - related liver fibrosis, and determine the diagnostic thresholds for each fibrosis stage." (PMID 40352927, 2025). "Another gene that was significantly upregulated in cirrhosis compared to healthy controls and NAFLD patients was CHI3L1, which was previously found to be increased in inflammation, promoting angiogenesis, and may have diagnostic value for liver fibrosis." (PMID 40489530, 2025). "Additionally, CHI3L1 can predict the risk of non-alcoholic steatohepatitis, the progression of hepatic fibrosis, and the prognosis of alcoholic liver disease and hepatocellular carcinoma." (PMID 40821115, 2025). "In conclusion, by inhibiting hepatic macrophage aggregation and promoting apoptosis, CHI3L1 deficiency could ameliorate hepatic fibrosis; thus,CHI3L1 can serve as a potential therapeutic target for liver fibrosis." (PMID 38962736, 2024). "Moreover, fibrosis progression seems to be under genetic control, and the Chi3l1-131G → C promoter polymorphism is reported to be associated with the severity of HCV-induced liver fibrosis through the determination of Chi3l1 serum levels." (PMID 39769202, 2024). "However, the serum CHI3L1 level alone has little diagnostic value for early liver fibrosis and tends to increase with age." (PMID 38962736, 2024). "A random-effects model was used to determine the diagnostic accuracy of serum CHI3L1 for diagnosing stages of liver fibrosis, because heterogeneity (I2 values for sensitivity, specificity, PLR, NLR, and DOR) for fibrosis stages F2, F3, and F4 was greater than 50%." (PMID 35360517, 2022). "Measurement of serum CHI3L1 is a feasible diagnostic tool for liver fibrosis." (PMID 35360517, 2022). "As suggested in prior research, CHI3L1 may be adopted to diagnose cirrhosis or liver fibrosis caused by viral hepatitis and alcoholic hepatitis, and it could accurately distinguish among different stages of LF." (PMID 33082884, 2020). "The expression of chitinase 3-like 1 by hepatic stellate cells, which was positively associated with cell survival and negatively with liver fibrosis, might be enhanced by MSC-derived IL-6." (PMID 27409608, 2016).